MC4R (melanocortin 4 receptor)
Diseases named in the same sentence as MC4R in open-access papers (continued):
Sharing a sentence is not in itself a finding about the gene and the disease.
Obesity (continued). "In a cohort of Czech children and adolescents with obesity, carriers of MC4R mutations (n = 5) and noncarriers (n = 96) had a similar weight reduction following a 3 or 6 weeks weight reduction program." (PMID 32921795, 2021). "A 1-year obesity intervention program in German children carrying MC4R mutations (n = 9) and noncarriers (n = 46) also showed similar weight reductions in carriers and noncarriers following intervention." (PMID 32921795, 2021). "We observed particularly low penetrance of MC4R for obesity (<55% for BMI ≥ 30 kg/m2), consistent with previous findings and particularly high penetrance for GCK-MODY (100% for diabetes or prediabetes in both studies, 95% CI’s 59–100% in AMP-T2D-GENES, 69–100% in UKB)." (PMID 34108472, 2021). "A GWAS study in Danish, Icelandic, Dutch, European Americans, and African American adults has shown that SNPs in the FTO, MC4R, BDNF, and SH2B1 genes are highly associated with obesity risk via modulating leptin secretion to induce leptin resistance in different ethnicities." (PMID 34836030, 2021). "Disruption of the MC4R gene leads to the obesity phenotype, which is related to T2DM." (PMID 34696776, 2021). "We compared methylation profiles in sperm quantified by bisulfite pyrosequencing, at promoter-associated CpG sites of genes involved in metabolism including fat mass and obesity-associated (FTO) and melanocortin-4 receptor (MC4R) from six vegans and 34 omnivores." (PMID 33767672, 2021). "On the contrary, among Mizo, the risk caused by the interaction of FTO rs9939609 and MC4R rs17782313 for obesity was enhanced, albeit with no statistical significance." (PMID 34414818, 2021). "In men, physical activity attenuated the effect of the MC4R rs17782313 on obesity." (PMID 34205732, 2021). "Setmelanotide is a melanocortin 4 receptor (MC4 receptor) agonist that effectively treats obesity without the adverse cardiovascular effects caused by other MC4 receptor agonists." (PMID 34066399, 2021). "Our previous study in cultured cells demonstrated the efficacy of membrane-permeant MC4R-selective PCs to restore cell surface expression and function of MC4R mutant forms, paving the way toward the development of a therapy targeting patients with MC4R-related obesity." (PMID 33434184, 2021). "The melanocortin-4 receptor (MC4R), a hypothalamic master regulator of energy homeostasis and appetite, is a class A G-protein-coupled receptor and a prime target for the pharmacological treatment of obesity." (PMID 34561620, 2021). "A member of the family, SLC4 influences MC4R dependent satiety and the loss of MC4R function leads to prolonged obesity and reduced energy expenditure, while mice lacking SLC4 display anorexia." (PMID 33472578, 2021). "Genetic studies demonstrated that single nucleotide polymorphisms (SNPs) in the MC4R, LEP, and LEPR genes could be linked with obesity." (PMID 34205732, 2021). "For obesity, the difference in BMI between MC4R monogenic variant carriers and the top 1% BMI gePS was not significant." (PMID 34108472, 2021). "In contrast to noncarriers, carriers of damaging or unresolved MC4R mutations failed to reduce their BMI SDS during obesity treatment, indicating a need for personalized treatment based on the MC4R genotype." (PMID 32921795, 2021). "In another view, individuals who have mutant allele of both genes may be neutral towards obesity, because the positive effect of the FTO rs9939609 gene polymorphism is reduced by the MC4R rs17782313." (PMID 34414818, 2021). "In contrast, among adults with obesity, carriers of MC4R mutations are heavier than their noncarrier counterparts, indicating that MC4R-induced obesity leads to a more severe phenotype in adulthood." (PMID 32921795, 2021).
Obesity (continued). "Taken as a whole, these data show that the insertion of either WT- or R165W-hMC4R in the mouse MC4R locus led to 2 obesity models that recapitulated several of the characteristics observed in obese patients with MC4R deficit, albeit with a modestly lower penetrance for the WT human allele." (PMID 33434184, 2021). "Additionally, BBS and Alström syndrome are both characterized by early-onset obesity and hyperphagic behaviors likely due at least in part to defects in the MC4R signaling pathway." (PMID 34013094, 2021). "Thus, re-expression of MC4R in cholinergic neurons of MC4R knockout mice led to obesity-induced hypertension." (PMID 34512392, 2021). "Monogenic obesity results from highly infrequent single genes mutations (such as LEP, POMC); however, some of them also demonstrated an association with polygenic obesity (e.g., MC4R, FTO)." (PMID 34445769, 2021). "Therefore, the development of an MC4R agonist has been regarded as a therapeutic option for human obesity treatment." (PMID 33807040, 2021). "It has been shown that HEK293 cells are transiently transfect with the mutant melanocortin 4 receptor (MC4R), a rhodopsin-like GPCR expressed in the hypothalamic pro-opiomelanocortin (POMC) neurons and the gene most commonly linked to obesity, which is located on chromosome 18q21.31at an early age." (PMID 34835958, 2021). "In this study, we detected 30 naturally occurring MC4R variants that to our knowledge have not been previously reported to be associated with obesity and are predicted to be damaging by at least one functional algorithm." (PMID 32952152, 2021). "The findings from the present study provide no consistent statistically significant evidence for an association of the five investigated obesity-associated genes (FTO, TMEM18, MC4R, SEC16B, and BDNF) with baseline anthropometric traits or their changes after 12 months of behavioural intervention." (PMID 33801339, 2021). "Most associated genes that are reported to be associated with obesity are – FTO rs9939609 and MC4R rs17782313, recent studies also reported ACE I/D rs4646994 and MTHFR C677T rs1801133 gene polymorphisms to be associated with obesity specifically in Indian population." (PMID 34414818, 2021). "Few studies investigated the possible differences in response to obesity treatment between MC4R mutation carriers and noncarriers in children." (PMID 32921795, 2021). "Mutations in genes that have a physiological role in the hypothalamic leptin–melanocortin energy balance system, such as mutations in leptin, leptin receptor, POMC, prohormone 1/3 convertases (PC1/3), MC4R, are related to the currently known monogenic forms of obesity." (PMID 33261141, 2020). "The intracerebroventricular (icv) or intraperitoneal (ip) injection of MC4R agonists can decrease food intake in goldfish, zebrafish, and coho salmon, while transgenic zebrafish over-expressing AgRP display obesity, increased linear growth, and adipocyte hypotrophy." (PMID 32987823, 2020). "In addition to early-onset obesity, a higher prevalence of ADHD has been reported in MC4R mutation carriers." (PMID 31896117, 2020). "This suggests that the genetic and/or nongenetic mechanisms that counteract the obesity-increasing effects of MC4R mutations in carriers of normal weight act throughout the life course." (PMID 32692746, 2020). "Interesting novel developments are clinical trials with MC4R-agonists in patients with leptin-melanocortin pathway deficiencies, e.g. POMC and LEPR deficiency, and glucagon-like peptide 1 (GLP-1) agonists for adolescents with obesity." (PMID 32384097, 2020). "In addition, we show that the impact of even highly penetrant MC4R mutations may be at least partially mitigated by a low polygenic susceptibility to obesity and potentially healthier environments and behaviors, blurring the lines between monogenic and polygenic forms of obesity." (PMID 32692746, 2020).
Obesity (continued). "Furthermore, some genes involved in the pathogenesis of obesity such as the melanocortin-4 receptor gene, responsible for the most frequent form of monogenic obesity induced by a single gene mutation, have been identified." (PMID 32414136, 2020). "A recent study reported that MC4R gene may contribute the co-occurrence of coronary artery disease and obesity." (PMID 32807123, 2020). "However, this Korean cohort showed that the rs17782313 SNP in the MC4R gene is related to diabetes and obesity." (PMID 32807123, 2020). "In addition, MC4R-knockout mice display obesity, hyperphagia, hyperinsulinemia, and hyperglycemia, providing further evidence that MC4R has a role in the regulation of energy homeostasis." (PMID 32733386, 2020). "A number of obesity case-control studies have found variations in the MC4R gene." (PMID 31888951, 2020). "Previous evidence of animal studies has revealed that any defect and disruption in MC4R gene may be lead to obesity-related phenotypes." (PMID 32019489, 2020). "For instance, MC4R knockout mice lack the ability to properly maintain energy homeostasis and, for this reason, may be more prone to obesity." (PMID 33817246, 2020). "Some of the genes associated with monogenetic severe obesity are: leptin (LEP), leptin receptor (LEPR), proopiomelanocortin (POMC), MC4R, preproconvertase 1 (PCSK1), single minded 1 (SIM1), brain-derived neurotrophic factor (BDNF), and tyrosine kinase receptor tropomycin-related kinase B (TrkB)." (PMID 32982666, 2020). "First, the scRNA-seq data analyzed here were derived from late postnatal, adult and predominantly wild-type mice; future work is needed to assess the role of Pomc+, Agrp+ and Mc4r+ and other hypothalamic cell types during developmental stages and relevant obesogenic perturbations in human obesity." (PMID 32955435, 2020). "In monogenic non-syndromic obesity, the identification of an MC4R mutation seems to be no contraindication for bariatric surgery." (PMID 32729070, 2020). "The three patients (0.65%) with missense mutations in MC3R had a similar degree of obesity, which was milder than those harbouring RSVs in MC4R, and no overgrowth or advanced skeletal maturation." (PMID 30926952, 2020). "Conversely, blockade of MC4R by the agouti-related protein (AgRP) increases feeding, and complete loss of MC3R or MC4R in mice is associated with increased food intake and concomitant obesity." (PMID 32109250, 2020). "Mutations in MC4R that render the receptor less- or non-responsive to POMC-derived peptides are commonly associated with human obesity." (PMID 32109250, 2020). "However, heterozygous Sim1+/– mice are viable, presenting an early-onset obesity, hyperphagia, and increased linear growth, similar to Mc4r-mutant mice." (PMID 32982666, 2020). "Despite the fact that the mechanisms behind the effect of MC4R rs17782313 on obesity and its related metabolic phenotypes are less understood, there is a suggestion that this variant may play an important role in central appetite control and eating behaviors." (PMID 32758123, 2020). "The rs17782313 variant near MC4R has previously been reported to be associated with obesity in various populations, but not yet in a Kuwaiti population." (PMID 32733386, 2020). "Furthermore, marked MC4R downregulation was observed in an animal model of obesity, in agreement with the phenotype of the MC4R knockout mice, suggesting a role for MC4R in energy metabolism." (PMID 33817246, 2020). "We also evaluated modification of the relationship of MC4R and cardiovascular disease by obesity." (PMID 32807123, 2020). "In addition, it is necessary to investigate other genes (isolated or associated) which have been demonstrated to be involved in obesity such as FTO, Melanocortin 4 Receptor - MC4R, Adenovirus 36 and beta 2 adrenoceptor-ADRB2." (PMID 32457643, 2020). "The MC4R is a promising target for drugs to treat obesity or sexual dysfunction." (PMID 32785054, 2020).
Obesity (continued). "Importantly, while α-MSH/IgG IC from all subjects were binding and activating MC4R, the receptor binding affinity was decreased in obesity." (PMID 30755592, 2019). "We believe that our study may help to understand better the impact of MC4R gene on obesity development, and to help to provide personalized prevention/treatment strategies to fight against obesity and its metabolic consequences." (PMID 30945034, 2019). "MC4R gene is the most common single-gene effect of human obesity." (PMID 32116676, 2019). "However, no clear genetic alterations, including of genes involved in MC4R signaling, have been detected in the major forms of obesity and ED12." (PMID 30755592, 2019). "In addition to MC4R, loci in the FTO gene have been consistently linked with the risk of obesity with FTO being highly expressed in the hypothalamus and playing a role in the ghrelin, leptin, and melanocortin pathways." (PMID 30764585, 2019). "Our study pointed out the role of MC4R rs17782313 and ENPP1 rs1044498 in maternal and neonatal obesity risk in correlation with BMI, MUAC and TST and BIA, which could be useful for diagnosing obesity in mother-newborn couples." (PMID 31350533, 2019). "We next performed genetic association studies with a series of primary phenotypes recorded in UK Biobank: BMI and obesity, hemodynamic phenotypes known to be affected by MC4R signaling (resting heart rate, systolic and diastolic BP), and risk of type 2 diabetes and coronary artery disease." (PMID 31002796, 2019). "Among the multiple MCR genes that proved to be involved in the etiology of obesity, MC4R is associated with monogenic obesity, regardless of age15." (PMID 31350533, 2019). "Nevertheless, carrying the infrequent allele at MC4R Ile251Leu seems not to have an influence on eating behavior compared to children with obesity and variations in the MC4R gene." (PMID 31035493, 2019). "We hypothesized that a more refined understanding of MC4R signaling and its impact on clinical phenotypes in the general population may inform the design of drugs targeting this pathway to treat common obesity and its complications." (PMID 31002796, 2019). "In the current study, targeted resequencing of the coding regions of 31 selected genes known to be involved in monogenic forms of obesity (excluding LEP, LEPR and MC4R) was performed in 23 probands from Pakistani families with severe early-onset obesity segregating as an autosomal recessive trait." (PMID 31488071, 2019). "This is in concordance with previous studies among PCOS women, they have perceived that there is an association between MC4R SNPs (rs12970134 and rs17782313) and obesity whereas the SNPs are not risk factors for PCOS." (PMID 31429705, 2019). "However, the diverse nature of MC4R-driven pharmacological efficacy has posed challenges in developing an MC4R agonist for the treatment of obesity." (PMID 31100979, 2019). "Based on our comparator data, it is possible that the peptidic MC4R agonists capable of inducing MC4R internalization may be considered suitable drug candidates for therapeutic intervention for the treatment of obesity." (PMID 31100979, 2019). "Moreover, acting in the hypothalamus, and particularly through the receptor TrkB, BDNF can attenuate diet-induced obesity through a mechanism related to MC4R signaling." (PMID 29316939, 2018). "Although mutations in MC4R lead to the most common form of monogenic obesity, not all variants are linked to obesity." (PMID 29991773, 2018). "These forms present complete penetrance in comparison to the particular form of obesity related to MC4R, and probably MC3R as well; polymorphisms in these genes are associated with forms of obesity that are more severe than typical polygenic obesity but less severe than homozygous gene mutations." (PMID 30338250, 2018).
Obesity (continued). "According to the results of several studies, the individuals at high risk for obesity development may be homozygous for both FTO and MC4R genes or may be homozygous for one of the two genes and heterozygous for the other." (PMID 30338250, 2018). "The research conducted among the Japanese revealed that the minor C allele of the MC4R rs17782313 polymorphism had significant positive effects on the TG level, but was not related to obesity or BMI." (PMID 29315078, 2018). "The aim of the present study was to assess the independent contributions of LEPR (rs1137101), FTO (rs9939609), MC4R (rs2229616 and rs17782313), and PPARG-2 (rs1801282) polymorphisms for clinically overweight or obesity phenotypes and endocrine-metabolic traits in prepubertal children." (PMID 29679223, 2018). "Human hypothalamic POMC neurons might also produce β-MSH, which is associated with human obesity when mutated and inhibits feeding as potently as α-MSH when injected into mice by activating MC4R." (PMID 30201275, 2018). "While our findings are consistent with the lack of an increase in EE (in the PV group relative to the PS group) in Mc4r−/− mice, SVD was still able to exert a robust weight-reducing effect; thus, underscoring the impact of the vagus nerve on the Mc4r obesity phenotype." (PMID 29545738, 2018). "Mutations in human KSR2, MC4R, LEP and LEPR have been described as monogenic causes of obesity, confirming that this screen has relevance to human monogenic obesity disorders." (PMID 30563851, 2018). "However, when looking at childhood obesity, MC4R mutant carriers have a higher percentage body fat composition of 67.0 vs 45.5% in other obese children." (PMID 30121879, 2018). "Most notably, human obesity has been associated with mutations in leptin (LEP), leptin receptor (LEPR), prohormone convertase 1 (PC1), proopiomelanocortin (POMC) and melanocortin-4 receptor (MC4R)." (PMID 30068297, 2018). "Furthermore, neuroimaging studies have demonstrated altered brain reward responses to food stimuli in patients with monogenic forms of obesity and in individuals with common risk alleles of obesity-associated genes (such as FTO and MC4R)." (PMID 28597337, 2018). "Bariatric surgery is currently the only successful option in treating obesity, but when bariatric surgery has been performed on homozygous mutant MC4R patients, it had no impact on long-term weight loss." (PMID 30121879, 2018). "Haploinsufficiency in MC4R is the most common form of monogenic obesity." (PMID 29991773, 2018). "A comprehensive understanding of molecules that act at MC4R may help to design safe and effective anti-obesity drugs." (PMID 29910730, 2018). "In addition, the authors also identified that both MC4R and FTO risk genotypes increase the metabolic risk in children with obesity." (PMID 30338250, 2018). "Hence our decision to analyze relationships between particular components of MetS and selected gene polymorphisms, namely peroxisome proliferator-activated receptor gamma (PPAR-γ), fat mass and obesity-associated (FTO), and melanocortin-4 receptor (MC4R)." (PMID 29315078, 2018). "The top loci in this cluster include the well-known obesity-associated loci FTO and MC4R." (PMID 30240442, 2018). "Background/Objectives: We tested the hypothesis that abolishing vagal nerve activity will reverse the obesity phenotype of melanocortin 4 receptor knockout mice (Mc4r−/−)." (PMID 29545738, 2018). "Whereas obesity due to MC4R mutations is evident as of early age – most notably in homozygotes, the metabolic consequences emerge only later in life." (PMID 30068297, 2018). "Comparable weight loss effects have been observed in genetic animal models of obesity treated with Setmelanotide, although not in MC4R knockout mice, indicating that the effects of Setmelanotide are indeed due to its action on MC4R." (PMID 29031731, 2017).